DEK (DEK proto-oncogene)
Diseases named in the same sentence as DEK in open-access papers (continued):
Sharing a sentence is not in itself a finding about the gene and the disease.
Huntington disease (2 papers, 2022 to 2025). Huntington disease (HD) is a rare neurodegenerative disorder of the central nervous system characterized by unwanted choreatic movements, behavioral and psychiatric disturbances and dementia. "DEK was among a small group of genes found to be differentially expressed between pre-symptomatic and symptomatic Huntington’s disease." (PMID 36275000, 2022). "DEK was also identified as a hub gene in the comparison of differentially expressed genes between Huntington’s disease patients and healthy controls." (PMID 36275000, 2022).
leiomyosarcoma (2 papers, 2022 to 2025). An uncommon, aggressive malignant smooth muscle neoplasm, usually occurring in post-menopausal women. "Additionally, KIF15 recruits and promoted the binding between USP15 and DEK, facilitating the proliferation of leiomyosarcoma cells by preventing DEK degradation." (PMID 40087774, 2025). "USP15 interacts with DEK and the kinesin family member 15 (KIF15) and stabilizes DEK to facilitate the proliferation of the leiomyosarcoma cell lines SK-UT-1 and SK-LMS-1." (PMID 35203682, 2022).
metastatic colorectal cancer (2 papers, 2014 to 2018). "The overall data presented here clearly point to a new role of DEK oncogene as a clear factor for the maintenance of the aggressive phenotype in metastatic colorectal cancer and as a potential marker of irinotecan-based therapy response for KRASwt patients." (PMID 25515240, 2014). "High DEK expression has been described previously by our group as a crucial event for aggressive tumour phenotype and as a biomarker for poor response to irinotecan in metastatic colorectal cancer." (PMID 29409457, 2018). "This study aims to analyze the role of DEK in metastatic colorectal cancer." (PMID 25515240, 2014).
multiple myeloma (2 papers, 2016 to 2017). "Although the same chromosomal amplification occurs in multiple myeloma (MM), a plasma cell neoplasm, whether the expression and the copy number of the DEK gene are affected in MM remains elusive." (PMID 28558048, 2017).
myeloid leukemia (2 papers, 2014 to 2020). A clonal proliferation of myeloid cells and their precursors in the bone marrow, peripheral blood, and spleen. "The human DEK oncogene was first discovered as a fusion with the gene encoding the CAN nucleoporin protein in myeloid leukemia patients." (PMID 32736520, 2020).
neuroblastoma (2 papers, 2007 to 2023). Neuroblastoma (NB) is the most common solid, extracranial childhood tumor. "The identification of DEK as a tumor-associated antigen in murine neuroblastoma cell lines is fascinating due to the expression of DEK in an expanding number of human cancers." (PMID 17397536, 2007). "Of note, DEK is indeed over-expressed in the neuroblastoma cell lines tested." (PMID 17397536, 2007).
neuroendocrine carcinoma (2 papers, 2013). A malignant neuroendocrine neoplasm composed of cells containing secretory granules that stain positive for NSE and chromogranin. "Shibata, et al19 also showed that DEK overexpression, partly through an increase in its gene dose, mediates the activity of global transcriptional regulators and is associated with tumor initiation activity and poor prognosis in high-grade neuroendocrine carcinoma." (PMID 24353627, 2013).
non-small cell lung carcinoma (2 papers, 2018 to 2022). A group of at least three distinct histological types of lung cancer, including non-small cell squamous cell carcinoma, adenocarcinoma, and large cell carcinoma. "In human ESCC, HNSCC, breast, bladder, colorectal, hepatocellular, and non-small cell lung carcinoma, DEK protein levels were increased in tumor versus adjacent normal tissue, and the extent of overexpression was variable." (PMID 29538372, 2018).
NUT carcinoma (2 papers, 2023 to 2025). "For example, carcinomas comprise conventional squamous cell carcinomas, NUT carcinomas, DEK::AFF2 carcinomas, EBV- and HPV-associated carcinomas, undifferentiated as well as SWI/SNF complex deficient sinonasal carcinomas, highlighting the variety of different morphologies and molecular pathogeneses." (PMID 37118352, 2023). "We report the case of a 32-year-old patient with an unusual NUT carcinoma originating in the maxillary sinus, which showed extensive well-differentiated, papillary squamous morphology, similar to the spectrum of the recently described DEK::AFF2 fusion-associated carcinoma." (PMID 37118352, 2023). "In recent years, multiple molecularly defined entities have emerged in head and neck pathology, especially among sinonasal squamous and basaloid carcinomas, including NUT carcinoma, SWI/SNF-deficient carcinoma, and DEK::AFF2 carcinoma." (PMID 40494991, 2025).
prostate adenocarcinoma (2 papers, 2015 to 2017). "Positive correlations between CELF1 and DEK mRNA expression in uveal melanoma and ten additional tumor types (including diffuse large B cell lymphoma, thyroid carcinoma or prostate adenocarcinoma) further reinforce the translational relevance of our results." (PMID 29269732, 2017). "Among hormonal naïve prostate adenocarcinoma models, LTL331 showed higher expression of DEK compared to the other models (e.g., LTL311, LTL313B and LTL418) that did not give rise to NEPC after host castration." (PMID 25544761, 2015).
rheumatoid arthritis (2 papers, 2015 to 2022). A chronic, systemic autoimmune disorder characterized by inflammation in the synovial membranes and articular surfaces. "By blocking the DEK protein, DEK-targeted aptamers (DTAs) can reduce the formation of neutrophil extracellular traps (NETs) to reveal a strong anti-inflammatory efficacy in rheumatoid arthritis." (PMID 35928230, 2022). "They identified elevated frequency of anti-DEK positivity not only in JIA, SLE, sarcoidosis, and rheumatoid arthritis patient sera but also in systemic sclerosis, polymyositis, and tuberculosis patient sera." (PMID 26425120, 2015).
serous ovarian cancer (2 papers, 2017 to 2022). "Additionally, DEK is overexpressed in high-grade serous ovarian cancers (HGSOCs), and reducing DEK levels significantly reduces cell viability and tumor growth, resulting in apoptotic cell death." (PMID 35742899, 2022).
systemic lupus erythematosus (2 papers, 2015 to 2020). An autoimmune multi-organ disease typically associated with vasculopathy and autoantibody production. "Autoantibodies that recognize DEK have been detected in the sera of patients with autoimmune diseases, such as systemic lupus erythematosus (SLE) and adolescent idiopathic arthritis (JIA)." (PMID 33584645, 2020).
transitional cell carcinoma (2 papers, 2011 to 2017). A malignant neoplasm arising from the transitional epithelium, usually affecting the urinary bladder, ureter, or renal pelvis. "We examined the expression of DEK protein by western blot in 38 paired transitional cell carcinoma (TCC) bladder tumor tissues and adjacent normal tissue." (PMID 21663673, 2011).
adenoma (1 paper, 2025). A neoplasm arising from the epithelium. "FBXW7 loss promotes intestinal tumorigenesis by enhancing proliferation, disrupting differentiation, causing DEK accumulation, altering TPM splicing, and accelerating adenomas with APC deficiency." (PMID 41373479, 2025).
allergic asthma (1 paper, 2020). A asthma with a basis in a pathological type I hypersensitivity reaction. "In this study, we showed that silencing DEK significantly attenuated the activation of the PI3K/AKT/mTOR pathway, indicating that DTA‐64 could reduce the development of allergic asthma through the PI3K/AKT/mTOR pathway." (PMID 33124760, 2020).
allergic disease (1 paper, 2025). An immune response that occurs following re-exposure to an innocuous antigen, and that requires the presence of existing antibodies against that antigen. "Several studies have documented the close association of RhoA with allergic diseases, whereas one study has indicated the regulatory effect of DEK on RhoA." (PMID 39668431, 2025).
Alpha-thalassemia (1 paper, 2026). Alpha-thalassemia is an inherited hemoglobinopathy characterized by impaired synthesis of alpha-globin chains leading to a variable clinical picture depending on the number of affected alleles. "Transcriptome analyses revealed that DEK and chromatin remodeler alpha thalassemia/mental retardation syndrome X‐linked chromatin remodeler have opposing effects on gene expression." (PMID 41239559, 2026).
bladder tumors (1 paper, 2011). "We evaluated DEK protein levels in bladder tumor tissues and found high levels of DEK protein in tumor tissue with no expression in adjacent normal bladder tissue." (PMID 21663673, 2011). "We wanted to test if DEK protein is expressed in bladder tumor tissue samples as compared to adjacent normal tissue." (PMID 21663673, 2011). "Eighty-six percent (86%) of bladder tumor tissues were found to be positive for DEK protein expression." (PMID 21663673, 2011). "cDNA microarray analysis of bladder tumor tissues found DEK as one of the genes significantly overexpressed in early stage bladder tumors." (PMID 21663673, 2011). "Previous studies based on tissue microarray data indicated that DEK mRNA is overexpressed in bladder tumors." (PMID 21663673, 2011). "Several studies indicated that DEK is overexpressed in bladder tumors." (PMID 21663673, 2011). "Our data indicates that DEK protein is present only in bladder tumor tissue." (PMID 21663673, 2011). "The DEK protein is expressed in 33 of 38 bladder tumor tissues with no expression in adjacent normal tissue." (PMID 21663673, 2011). "This pilot study demonstrated that DEK protein is over-expressed in bladder tumor tissue but not in adjacent normal tissue." (PMID 21663673, 2011).
breast tumor (1 paper, 2016). "Taken together, these data indicate that DEK enhances breast tumor growth and angiogenesis in HIF-1α-dependent and -independent manners." (PMID 26988756, 2016).
cystitis (1 paper, 2011). Inflammation of the urinary bladder. "We cannot rule out the possibility that DEK protein may be present in the bladder tissue of patients with cystitis." (PMID 21663673, 2011).
esophageal cancer (1 paper, 2025). A primary or metastatic malignant neoplasm involving the esophagus. "Decreased levels of COL4A1, DEK, GINS1, HPCAL1, KIF4A and RBMX predicted longer survival in esophageal cancer patients, while overexpression of IGFL1P1, LRRC57A-AS1, SNHG3, ULK3 and ZFYVE19 correlated with longer survival." (PMID 41326355, 2025). "The results showed that COL4A1, DEK, GINS1, HPCAL1, KIF4A and RBMX were significantly increased in esophageal cancer tissues and decreased in the combined treatment group, suggesting that are potential prognostic markers." (PMID 41326355, 2025).
glioma (1 paper, 2023). A benign or malignant brain and spinal cord tumor that arises from glial cells (astrocytes, oligodendrocytes, ependymal cells). "Furthermore, the chromobox protein homolog 3 (CBX3), DEK proto-oncogene (DEK), and DEAD (Asp-Glu-Ala-Asp) box polypeptide 39B (DDX39B) transcripts and proteins were up-regulated in glioma versus normal brain tissues." (PMID 37762371, 2023).
inverted papilloma (1 paper, 2025). An endophytic benign papillary epithelial neoplasm that results from the invagination and proliferation of epithelial cells in the underlying stroma. "Additionally, a 52-year-old non-smoking female, initially diagnosed with inverted papilloma in the ethmoid sinus, experienced multiple recurrences in the sinonasl tract over 24 years, ultimately presenting with a tracheal mass harboring DEK::AFF2 fusion." (PMID 40299135, 2025).
rectal cancer (1 paper, 2018). A primary or metastatic malignant neoplasm that affects the rectum. "Moreover, the fact that DEK expression associated with the pro-apoptotic factor P38 supports the role of DEK as a predictive biomarker for pathological complete response to chemoradiotherapy prior to surgery in rectal cancer patients." (PMID 29409457, 2018).
renal carcinoma (1 paper, 2011). A carcinoma arising from the epithelium of the renal parenchyma or the renal pelvis. "However, we also detected DEK protein in the urine of some prostate and renal cancer patients indicating that DEK protein may be overexpressed in some prostate and renal cancer tumors." (PMID 21663673, 2011).
schizophrenia (1 paper, 2025). A major psychotic disorder characterized by abnormalities in the perception or expression of reality. "The human DEK gene is located within a schizophrenia risk locus (6p23), and previous studies have linked DEK to molecular features of neurodegeneration, including tau pathology." (PMID 41282170, 2025).
skin cancer (1 paper, 2018). "Additionally, high DEK expression is associated with poor prognosis in melanoma, gastric, ovarian, breast, prostate, bladder, lung, pancreatic, skin cancer, and head and neck SCC." (PMID 29538372, 2018).
tongue tumors (1 paper, 2017). "Tongue tumors overexpressing DEK showed increased proliferating cell nuclear antigen and elongator complex protein 3 expression." (PMID 28834425, 2017). "Moreover, in iDek (DOX‐inducible Dek) mice exposed to a carcinogen, DEK overexpression stimulated crucial oncogenic processes, such as DNA replication and cell cycle progression, in precancerous lesions, thereby promoting malignant transformation of tongue tumors." (PMID 28834425, 2017). "To clarify whether DEK overexpression contributed to the progression of malignant lesions via cellular senescence in our model, we investigated mRNA expression profiles using an RT2 Profiler PCR Array (Mouse Aging set) in tongue tumors from DOX+ iDek and DOX‐ iDek mice (n = 3 each)." (PMID 28834425, 2017).
viral infections (1 paper, 2015). "Nonetheless, it is unclear what links these persistent viral infections that require or increase DEK expression and the host's inflammatory responses to the viruses." (PMID 26425120, 2015). "In addition to being transcriptionally regulated in response to viral infection, DEK also controls the use and maintenance of viral genetic material during human immunodeficiency virus (HIV) and Kaposi's sarcoma-associated herpesvirus (KSHV) infections." (PMID 26425120, 2015). "We will discuss the role of DEK in viral infection and epitope presentation, which may provide mechanisms for both promoting intracellular viral oncogenesis and for eliciting T cell mediated immune responses that induce proinflammatory cytokines." (PMID 26425120, 2015).
cancer (68 papers, 2005 to 2025). A tumor composed of atypical neoplastic, often pleomorphic cells that invade other tissues. "Deletion of DEK causes cancer cell death, enhances the effect of an anticancer drug (tamoxifen) and slows tumor growth." (PMID 39984731, 2025). "We report two cases of DEK::AFF2 fusion-associated carcinomas managed at Saarland University Medical Center." (PMID 40688086, 2025). "DEK::AFF2 fusion-associated carcinomas of the sinonasal tract are exceedingly rare, with fewer than 100 cases reported worldwide, but probably underrecognized." (PMID 40688086, 2025). "DEK::AFF2 fusion-associated carcinomas are often initially misdiagnosed as inverted sinonasal papillomas due to their deceptively benign histological appearance." (PMID 40688086, 2025). "The particular molecular signature of DEK::AFF2 sinonasal fusion-associated carcinomas come along with unique clinical challenges, especially due to the absence of standardized therapeutic protocols." (PMID 40688086, 2025). "Although DEK is known to be implicated in epigenetic and transcriptional regulation, the details of these interactions and their relevance in cancer development remain largely elusive." (PMID 37550322, 2023). "In order to address the differential diagnosis of a DEK::AFF2 fusion-associated carcinoma, molecular profiling was performed using the FoundationOne® Heme test." (PMID 37118352, 2023). "DEK::AFF2 fusion-associated carcinomas have been described recently as an emerging entity in the sinonasal tract, with the majority showing a strikingly bland histologic appearance and overlap with so-called low-grade papillary Schneiderian carcinomas." (PMID 37118352, 2023). "A recently described molecularly distinct variant of SNSCC is the DEK::AFF2 fusion-associated carcinoma." (PMID 35326613, 2022). "Overexpression of DEK is associated with cancer cell proliferation and migration as well as chemoresistance." (PMID 34065619, 2021). "DEK encodes a DNA-binding protein that is a known oncogene in multiple other cancers, while E2F3 is crucial for transcriptional cell cycle control and is regulated by the RB protein pRB." (PMID 34283049, 2021). "DEK is a transcription factor involved not only in development and progression of different types of cancer, but is also associated with treatment response." (PMID 29409457, 2018). "The fact that DEK is overexpressed in many cancers, high DEK expression is associated with poor clinical outcome and DEK promotes tumor angiogenesis implicates the importance of DEK in cancer." (PMID 26988756, 2016). "To explore a potential mechanism underlying the role of DEK in cancer cell proliferation, we assessed the proportion of cells in each phase of the cell cycle when DEK expression was depleted or overexpressed." (PMID 27057626, 2016). "Kaplan-Meier estimate showed high DEK expression levels were strongly associated with the low patient survival in the carcinomas, which supports a notion that DEK plays a critical role in HCC progression." (PMID 27057626, 2016). "Among 10 candidates tested only MSH6, a DNA mismatch repair enzyme, and DEK, a chromatin- and RNA-associated protein mutated or overexpressed in certain cancers, showed reliable immunostaining results." (PMID 22824167, 2012). "Aberrant DEK overexpression has been linked to its anomalous association with mitotically defective chromosomes, micronuclei formation, and potentially oncogenic mutations, underscoring its role in cancer initiation." (PMID 38026229, 2023). "DEK protein overexpression is consistently associated with increased cell proliferation, tumor progression, poor prognosis of patients, and, consequently, advanced cancer stage." (PMID 37550322, 2023).